LYZ (lysozyme)
Diseases named in the same sentence as LYZ in open-access papers (continued):
Sharing a sentence is not in itself a finding about the gene and the disease.
triple-negative breast carcinoma (1 paper, 2025). An invasive breast carcinoma which is negative for expression of estrogen receptor (ER), progesterone receptor (PR), and human epidermal growth factor receptor 2 (HER2). "A transdifferentiation into osteoblast-like cells of a triple-negative breast cancer cell line, embedded into RPHy, was detected, while cell death was observed using RPHy-LYZ." (PMID 40046560, 2025). "This new photopolymerization process, using LED exposure, was achieved both in the presence (RPHy-LYZ) and in the absence (RPHy) of LYZ, producing potential cell-embedding hydrogels for inducing either a transdifferentiation process or the cell death of triple-negative breast cancer cells." (PMID 40046560, 2025).
tumor of salivary gland (1 paper, 2022). A neoplasm (disease) that involves the saliva-secreting gland. "S-100, mammaglobin, lysozyme and pan-TRK are all valuable IHC markers for the diagnosis of SC, but these antibodies seem not so specific since which can be expressed in some other tumors of salivary gland." (PMID 35094691, 2022).
ulcer (1 paper, 2025). "In subsequent analyses, we compared gene expression between DFU and non-ulcer samples within each annotated cell type and found that the difference in MPO and LYZ expression between DFU and control was most pronounced in keratinocyte clusters, whereas changes in other cell types were less marked." (PMID 41465092, 2025).
urinary tract infection (1 paper, 2026). "The high relative abundanceof antimicrobial proteins, such as lysozyme and cathelicidin, is consistentwith that found in another marine mammal suggesting a potential rolein protecting bottlenose dolphins from urinary tract infections." (PMID 41389023, 2026).
vitamin D deficiency (1 paper, 2024). A nutritional condition produced by a deficiency of VITAMIN D in the diet, insufficient production of vitamin D in the skin, inadequate absorption of vitamin D from the diet, or abnormal conversion of vitamin D to its bioactive metabolites. "Biochemical analysis showed possible vitamin D deficiency, low levels of pancreatic elastase and secretory IgA, high lysozyme levels; organic acid tests showed high tartaric acid and low serotonin; urine levels suggested high levels of toxic metals (lead, mercury, and cadmium)." (PMID 38649688, 2024).
Vogt-Koyanagi-Harada syndrome (1 paper, 2024).
volvulus (1 paper, 2022). "Expression of OLFM4 and LYZ was higher in patients with NEC in comparison to control infants suffering from volvulus (median score of the antibody OLFM4 (D1E4M): 1.25 and lysozyme: 2.0)." (PMID 35410162, 2022).
xanthoma (1 paper, 2009). A non-neoplastic disorder characterized by a localized collection of histiocytes containing lipid. "In popular xanthoma, histiocytes are CD68, KiM1p, and HAM 56 positive but negative for XVIIIa, S-100, lysozyme and CD56." (PMID 19814780, 2009).
ZIKV infection (1 paper, 2021). "A C-type lysozyme (LYSP, AAEL009670) and FREP20 (AAEL000726) were reduced 3.3 times and 5 times, respectively, by DENV2 infection and 2 times and 2.5 times, respectively, by ZIKV infection." (PMID 34880409, 2021).
infection (293 papers, 2008 to 2026). The state of being infected such as from the introduction of a foreign agent such as serum, vaccine, antigenic substance or organism. "The relationship between the higher antibacterial and lysozyme activities in the hemolymph of the primed animals observed 10 h post infection is likely to be the cause of the inhibited PO activity in this group of larvae." (PMID 38469316, 2024). "In vivo, barrier function analysis demonstrated that mice with an elevated lysozyme production had increased gut permeability at steady-state and during infection, whereas Lyz1-deficient mice exhibit significantly elevated barrier functions." (PMID 38823640, 2024). "Lysozyme g2 is encoded by the LYG2 gene, which is a lysozyme capable of host defense against infection, and IRG1L is a marker gene of the innate immune system." (PMID 38891577, 2024). "Better resistance to infection in sea bream was also linked to enhanced immune features (i.e. increased plasmatic lysozyme concentration) and growth." (PMID 38042956, 2023). "In fact, INSTI-treatment increased CD4 T cells in the patients and, at the same time, diminished the levels of lysozyme corroborating the association among lysozyme-inmune response and infection." (PMID 37653055, 2023). "The increase of this lysozyme in infected intestine suggests that after infection, these increased bacteria can destroy pathogenic bacteria and protect the health of the intestines." (PMID 36974664, 2023). "The same principle can be applied in our study in which the increase of phagocyte activity in grouper also increased the amount of secreted lysozyme during pathogenic infection as in Asian seabass, Lates calcarifer against Vibrio alginolyticus infection." (PMID 36138767, 2022). "In our study, DIV1 infection caused a significant decrease in LYZ (p < 0.001) and PO activity (p < 0.01), which meant that DIV1 inhibit the immune function of the host to a certain extent." (PMID 34512588, 2021). "Salivary antimicrobial proteins (sAMPs) such as lysozyme and lactoferrin protect the respiratory tract from invading microorganisms and have been linked with an increased infection risk in athletes." (PMID 30462646, 2018). "The effectiveness of lysozyme is also reduced in biofilms and in the chronically infected lung, due to electrostatic sequestration of the enzyme by infection-associated anionic biopolymers." (PMID 29980663, 2018). "We also present data showing that NGO1063 is exposed to the extracellular milieu, expressed during in vivo infection, and conserved in pathogenic and commensal Neisseria, highlighting the importance of this anti-lysozyme strategy during host colonization." (PMID 29975784, 2018). "This is in agreement with the observed susceptibility to infection of Atlantic salmon fed soybean, showing high levels of lysozyme and IgM in the mid- and distal-intestinal mucosa and an elevated gut inflammatory response." (PMID 26317431, 2015). "Contrary to expectations, lysozyme activity was highest in eggs from hotter, more arid locations, where we predicted the risk of trans-shell infection would be lower." (PMID 25057281, 2014). "Increase in lysozyme+ cells was observed during the experimental infections, which also can be associated with parasite killing." (PMID 25309902, 2014). "An increased expression of lysozyme has been shown to be associated with enhanced bacterial killing, decreased systemic dissemination and improved survival following infection." (PMID 19806192, 2009). "However, due to the mutations in genes such as oatA,17,20 lysozyme, albeit as the well-known antibacterial enzyme, doesn't combat the certain pathogenic infections, weakening its advantages in practical applications." (PMID 40912150, 2025). "Consequently, lysozyme plays a pivotal role in innate immunity, providing a first line of defense against pathogenic infections in mammals and other organisms." (PMID 40282767, 2025).
infection (continued). "Lysozyme, an integral part of the innate immune system in fish, exhibits lytic activity against pathogenic bacteria and demonstrates varying activity based on factors such as size, age, water temperature, pH, toxicity, infection, and stress level." (PMID 38328352, 2023). "LYZ gene encodes human lysozyme, which is a crucial biodefense effector in innate immunity and has lytic activity against bacterial peptidoglycan, thereby protecting the host from pathogenic infection." (PMID 37223018, 2023). "Immobilized lysozyme on PET can inhibit the graft-associated infection." (PMID 34943746, 2021). "Our results revealed that the elevated lysozyme activity in the jejunal mucosa caused by C. perfringens was reduced by arginine supplementation, likely because arginine alleviated the intestinal damage caused by the infection." (PMID 31428367, 2019). "In addition to rendering the invading bacterium more susceptible to lysozyme, treated infections would be cleared with greater efficiency by the enzyme, thereby minimizing, if not eliminating, downstream medical complications such as arthrogenicity." (PMID 31323733, 2019). "Moreover, the application of a charge-engineered lysozyme variant in a murine model of mucoid Pseudomonas aeruginosa lung infection was able to contrast both the burden of infection and the degree of tissue inflammation." (PMID 31694163, 2019). "Finally, ΔsliC bacteria were as fit as WT during competitive infections in a lysozyme-deficient mouse, which provided conclusive evidence that the inhibitory activity of SliC against host lysozyme is critical for gonococcal colonization." (PMID 30564232, 2018). "Finally, the synergistic effect of BP100 and lysozyme in the inhibition of infections caused by E. amylovora was confirmed in wounded pear leaves." (PMID 28212623, 2017). "RT-PCR and sequence analysis have previously indicated infection-associated down-regulation of transcripts for the ovine gastric lysozyme genes 1A, 2A, 3A and 4A, and confirmed these transcripts all exhibited some level of polymorphism (Anderson and Knight; data not shown)." (PMID 21682880, 2011). "In addition to the lysozyme responsible for ending the infection cycle, members of the T4 family generally encode a second lysozyme, usually related to the first, embedded in the central portion of key baseplate protein gp5." (PMID 21899740, 2011). "LYS-1 is a putative lysozyme, an antimicrobial protein, so we expected that loss of lys-1 might make the worm sensitive to infection in spite of possible redundancy with lys-2." (PMID 21209831, 2010). "However, it remains unclear how a gain- or loss-of-function in host lysozyme may impact the host inflammatory responses to pathogenic infection." (PMID 38823640, 2024). "However, it was unclear if a gain or loss of function in host lysozyme may impact the host–pathogen interaction thereby affecting the pathogenesis and inflammatory responses caused by infection." (PMID 38823640, 2024). "Nevertheless, these same microorganisms can cause infection of the ocular tissue due to imbalances in the immune and defence mechanisms of the eye itself, for example, physical barriers (eyelids and eyelashes), tear film with lactoferrin, lysozyme, and IgA (antimicrobial and anti-inflammatory)." (PMID 38003759, 2023). "We tested whether lysozyme and ovotransferrin activities varied in eggs of larks (Alaudidae) living along an arid-mesic gradient of environmental aridity, which we used as a proxy for risk of trans-shell infection." (PMID 25057281, 2014). "At 24 h post-infection, fish fed with the 0.12% BG diet maintained circulating leukocyte counts and displayed increased plasma lysozyme activity, indicating enhanced early immune readiness." (PMID 42088490, 2026). "Antioxidant and immune enzyme activities, including SOD, CAT, and MDA in the skin, gill, and liver, and LYZ and Na+/K+-ATPase in the skin and gill were monitored from 0 to 72 hours post-infection (hpi)." (PMID 40740775, 2025).
infection (continued). "The BL-99 strain enhanced nematode resistance to Gram-positive pathogens by upregulating the expression of lysozyme, saposin-like antimicrobial peptides, and c-type lectin family genes, thus enhancing the anti-infection ability and prolonging the life span." (PMID 41472063, 2025). "For comparison, bacterial (Paenibacillus larvae) and parasitic (Varroa destructor) infections also increase the level/activity of lysozyme in honeybees." (PMID 39813262, 2025). "In conclusion, the methanol extract of Raziz date palm pits showed an ability to inhibit the growth of S. agalactiae and was able to improve the immune activities, such as lysozyme and respiratory burst activity, during active infection." (PMID 41154759, 2025). "In vertebrates, including various fish species, IL-1β and IL-8 are key mediators of acute inflammation, coordinating the systemic response to infection and tissue damage, and activating antimicrobial defenses such as lysozyme and other cytokines." (PMID 41463874, 2025). "While plasma lysozyme levels in eastern oysters with mild P. marinus infections showed a slight decrease, this reduction became more pronounced with higher infection levels or with H. nelsoni protozoa." (PMID 41471258, 2025). "Phagocytic and lysozyme activity were significantly enhanced in the supplemented groups, indicating improved immune response post-infection Figure." (PMID 41188425, 2025). "Due to the presence of lysozyme as a natural antibiotic, the egg whites exhibit bactericidal properties, which are critical for protecting the developing embryo from infection." (PMID 40282767, 2025). "After siRNA treatment for 24 h, larvae were injected with Bt, and the mRNA levels of downstream AMP genes (attacin, gloverin, lebocin, lysozyme, and cecropin) were measured 12 h post-infection." (PMID 41463556, 2025). "Lysozyme is present constantly in G. mellonella larval hemolymph, but its amount can increase after infection." (PMID 40019037, 2025). "Among these, the proteins encoded by ORF67 and ORF203 mediate host lysis—holin, as a membrane protein, regulates infection cycle duration to ensure optimal lysis, while lysozyme degrades bacterial cell wall peptidoglycan to disrupt the membrane." (PMID 40762469, 2025). "Following exposure to Aeromonas hydrophila, the supplemented groups showed enhanced immune parameters, including higher WBC count, phagocytic activity, and lysozyme activity, demonstrating improved infection resistance." (PMID 41188425, 2025). "The infection rate, intensity of O. viverrini metacercaria, survival rates, immunoglobulin M (IgM) levels, lysozyme activity, and SOD levels in B. gonionotus were investigated." (PMID 41262377, 2025). "Serum lysozyme activity and immunoglobulin M levels also increased significantly in response to infection, indicating an active immune defense (p < 0.05)." (PMID 39684540, 2024). "The analysis of plasma parameters, especially the lysozyme activity, also confirmed a reduction in the infection of fish after three weeks of Protec Gill feeding." (PMID 38900829, 2024). "With an additional bactericidal function mediated by a separate protein domain, lysozyme is considered a uniquely important antimicrobial molecule contributing to the host's innate immune response to infection." (PMID 38823640, 2024). "PRR1 infection renders P. aeruginosa cells sensitive to lysozyme approximately 20 min before the drop in suspension turbidity starts." (PMID 38675985, 2024). "By targeting the bacterial cell walls, lysozyme helps prevent the colonization and infection of the chicken’s respiratory tract as well as gastro-intestinal system by harmful bacteria." (PMID 38400131, 2024). "The combination of chloroform and lysozyme results in the most efficient premature lysis of infected cultures, and such treatment late in the infection cycle yields a two-fold increase in the released PFUs." (PMID 38675985, 2024).
infection (continued). "When G. mellonella were fed with 105 CFU of P. entomophila, the amount of lysozyme was more than 50% reduced in comparison to its amount after infection with a lower 103 CFU dose." (PMID 38469316, 2024). "The results from the body fluid enzyme activity factor assay demonstrated significant activation of specific oxidative enzymes and lysozyme during the early phases of infection." (PMID 39760091, 2024). "In terms of lysozyme interaction with pathogenic bacteria, it was reported in mice that S. Typhimurium infection reduces lysozyme production in Paneth cells, and the infection stimulates Paneth cells to release lysozyme via a secretory autophagy pathway." (PMID 38823640, 2024). "As an integrative biomarker of immune status in fish, we analyzed the lysozyme known to play a key role in innate immunity by eliminating pathogens: lysozyme is produced and secreted by granulocytes and monocytes during pathogens and parasites infection." (PMID 38247008, 2024). "Later in infection, the gp5 lysozyme is inactivated by the T4 spackle protein which is secreted into the periplasm." (PMID 38675830, 2024). "By reporting a potentially deleterious role of host lysozyme in promoting inflammatory progression during infection, our study points to the potentially context-dependent mechanism underlying the host-pathogen interaction." (PMID 38823640, 2024). "PRR1 infection renders P. aeruginosa cells sensitive to lysozyme approximately 20 min before the start of a drop in suspension turbidity." (PMID 38675985, 2024). "We found that increased intestinal lysozyme production exacerbates the morbidity and mortality following infection while diminishing intestinal lysozyme unexpectedly dampens the inflammatory progression triggered by the infection." (PMID 38823640, 2024). "We observed here that PRR1 infection or the expression of the lysis protein from the plasmid renders PAO1 cells sensitive to lysozyme approximately 10–20 min before the start of normal lysis." (PMID 38675985, 2024). "Since the days of Alexander Fleming lysozyme has been recognized as an important component of protection early after infection with gram-positive bacteria." (PMID 38900248, 2024). "The activity of lysozyme was higher in primed larvae 3 h and 6 h after infection, while activity of phenol oxidase was lower 10 h after infection." (PMID 38469316, 2024). "Overall, these results reveal that B5 decreases the level of myeloperoxidase and promotes the production of lysozyme in the later infection phase." (PMID 39408834, 2024). "Lysozyme however significantly dropped two weeks after infection (p = 0.013, paired Wilcoxon signed-rank test) while lactoferrin did not change." (PMID 37862368, 2023). "The present findings are supported by studies observing elevations in humoral lysozyme activity in fish after experimental infection with A. hydrophila." (PMID 37893921, 2023). "The entire treated group showed increased lysozyme activity after infection in comparison to the control group." (PMID 37109557, 2023). "Other studies have documented lysozyme activity with E. ictaluri and F. covae during single infections." (PMID 36986384, 2023). "The lysozyme levels can be affected by factors like stress, infection, season, sex, sexual maturity, salinity, water temperature, pH, sedimentation, nutrition, toxicants, probiotics and immunostimulants." (PMID 36992186, 2023). "Our results suggest that both enzymes deacetylate the peptidoglycan cell wall, contributing to lysozyme resistance and increased virulence during infection." (PMID 36838272, 2023). "It is restricted to high multiplicity of infection conditions and involves the extracellular activity of a tail lysozyme." (PMID 38275943, 2023). "As their name indicates, originally these proteins were proposed to protect bacteria from host lysozyme during infection." (PMID 38047649, 2023).